HOXB5 (homeobox B5)
Diseases named in the same sentence as HOXB5 in open-access papers (continued):
Sharing a sentence is not in itself a finding about the gene and the disease.
glioma (4 papers, 2021 to 2024). A benign or malignant brain and spinal cord tumor that arises from glial cells (astrocytes, oligodendrocytes, ependymal cells). "Taken together, these results suggested that HOXB5 is overexpressed in glioma and associated with poor patient survival." (PMID 33858489, 2021). "In the present study, we firstly found that circATP5B and HOXB5 were overexpressed in glioma, especially in GSCs, and that circATP5B can upregulate HOXB5 expression via miR-185-5p sponging." (PMID 33858489, 2021). "In summary, our findings confirmed that HOXB5 is overexpressed in glioma and actively regulates the proliferation of GSCs." (PMID 33858489, 2021). "To confirm the possible downstream mechanism of HOXB5 on glioma, we performed GSEA based on the expression of HOXB5." (PMID 33858489, 2021). "We performed orthotopic xenografts to confirm the effects of the SRSF1/circATP5B/miR-185-5p/HOXB5 axis in glioma tumorigenesis in vivo." (PMID 33858489, 2021). "Pearson’s correlation analyses also confirmed a negative correlation between the expression levels of miR-185-5p and HOXB5 in each WHO grade glioma and in all glioma samples." (PMID 33858489, 2021). "HOXB5 was overexpressed in glioma and transcriptionally regulated IL6 expression and promoted the proliferation of GSCs via JAK2/STAT3 signaling." (PMID 33858489, 2021). "In summary, our results suggested that the SRSF1/circATP5B/miR-185-5p/HOXB5 axis regulates glioma tumorigenesis and proliferation in vivo." (PMID 33858489, 2021). "In glioma stem cells, circATP5B competitively sponges miR-185-5p, upregulating the expression of the homeobox gene HOXB5, which induces the proliferation of glioma stem cells through JAK2/STAT3 signaling." (PMID 34439740, 2021). "We found that the expression levels of HOXB5 in glioma tissues were higher than the adjacent brain tissues by qRT-PCR." (PMID 33858489, 2021). "Then, qRT-PCR, western blotting, and immunohistochemical analysis showed that HOXB5 expression was especially increased in higher glioma WHO grades." (PMID 33858489, 2021). "Besides, Pearson’s correlation analyses among clinical glioma specimens showed strong positive correlations between circATP5B and HOXB5 expression in each WHO grade glioma and among the total glioma samples." (PMID 33858489, 2021). "Therefore, the SRSF1/circATP5B/miR-185-5p/HOXB5 feedback loop is considered to be involved in glioma proliferation." (PMID 33858489, 2021). "In our study, we certified that HOXB5 was overexpressed in clinical glioma specimens and patient-derived primary GSCs, and the higher expression of HOXB5 correlated with a poorer prognosis in glioma patients, as confirmed by qRT-PCR, western blotting, and Kaplan–Meier survival analyses." (PMID 33858489, 2021). "Finally, we conclude that the SRSF1/circATP5B/miR-185-5p/HOXB5 feedback loop is involved in glioma tumorigenesis and proliferation." (PMID 33858489, 2021). "To confirm whether HOXB5 correlated with the proliferation of glioma, we firstly performed qRT-PCR and western blotting to detect the efficiency of HOXB5 knockdown or overexpression." (PMID 33858489, 2021). "Our study found that circATP5B could regulate HOXB5 expression via miR-185-5p sponging in glioma." (PMID 33858489, 2021). "However, whether HOXB5 regulates the proliferation of glioma and its specific mechanism in the proliferation of GSCs remains unclear." (PMID 33858489, 2021). "Therefore, our study found a novel feedback loop involving the SRSF1/circATP5B/miR-185-5p/HOXB5 axis that regulates the proliferation of GSCs and may provide a novel target for glioma therapy." (PMID 33858489, 2021). "Kaplan–Meier survival analyses showed that the median survival times of lower-grade glioma patients, GBM patients, or total glioma patients with higher HOXB5 expression were shorter than those for patients with lower HOXB5 expression." (PMID 33858489, 2021).
glioma (continued). "We also confirmed significantly positive correlations between HOXB5 and IL6 expression in each WHO grade glioma and among the total glioma samples." (PMID 33858489, 2021). "We also certified that there were significant positive correlations between HOXB5 and SRSF1 expression in clinical glioma specimens." (PMID 33858489, 2021). "However, the relationship between HOXB5 and glioma remains largely unknown." (PMID 33858489, 2021). "Moreover, Pearson’s correlation analyses among clinical glioma specimens revealed significant positive correlations between HOXB5 and IL6 expression in each WHO grade glioma and among the total glioma samples." (PMID 33858489, 2021). "In addition, Pearson’s correlation analyses among clinical glioma specimens showed significant positive correlations between HOXB5 and SRSF1 expression in each WHO grade glioma and among the total glioma samples." (PMID 33858489, 2021).
non-small cell lung carcinoma (4 papers, 2022 to 2025). A group of at least three distinct histological types of lung cancer, including non-small cell squamous cell carcinoma, adenocarcinoma, and large cell carcinoma. "Equally, miR-455-3p restrained non-small cell lung cancer cell proliferation and migration by directly binding to HOXB5 targeting and was a separate prognostic factor." (PMID 37400847, 2023). "In BC and non-small cell lung cancer (NSCLC), knockdown of HOXB5 significantly suppressed the β-catenin protein and its downstream targets c-Myc and CCND1, thereby inhibiting cell proliferation, migration, invasion, and EMT of the cancer cells." (PMID 34617205, 2022).
Obesity (4 papers, 2015 to 2024). Accumulation of substantial excess body fat. "HOXB5 was suggested to play a protective role in obesity by mitigating inflammation and promoting adipocyte turnover." (PMID 39296904, 2024). "To date, little is known about the functions of HOXB5 genes with obesity." (PMID 39296904, 2024). "The expression of PTX3, NCF2, HOXB5, ABCA6, and C1orf162 were upregulated in the placenta of mothers with obesity compared with mothers with normal BMI." (PMID 39296904, 2024).
pancreatic cancer (4 papers, 2021 to 2024). "Its expression is upregulated by Homeobox B5, a poor prognosis marker in pancreatic cancer." (PMID 35642012, 2022).
acute myeloid leukemia (3 papers, 2021 to 2025). Acute myeloid leukemia (AML) is a group of neoplasms arising from precursor cells committed to the myeloid cell-line differentiation. "Interestingly, our data demonstrate that HOXB5 and ZNF521 are co-expressed in myeloid progenitors, while others have reported their aberrant expression in corresponding acute myeloid leukemia." (PMID 37371852, 2023).
head and neck squamous cell carcinoma (2 papers, 2021 to 2022). A squamous cell carcinoma that arises from any of the following anatomic sites: lip and oral cavity, nasal cavity, paranasal sinuses, pharynx, larynx, and salivary glands. "In head and neck squamous cell carcinoma, HOXB5 plays an oncogenic role through the EGFR/Akt/Wnt/b-catenin signaling axis." (PMID 34440097, 2021). "In head and neck squamous cell carcinoma (HNSCC), HOXB5 functions as an oncogene, which binds directly to the promoter region of EGFR and regulates the AKT/Wnt/β-catenin synergistic signaling axis to enhance proliferation, cell migration, invasion, and EMT." (PMID 34617205, 2022).
leukemia (2 papers, 2021). A malignant (clonal) hematologic disorder, involving hematopoietic stem cells and characterized by the presence of primitive or atypical myeloid or lymphoid cells in the bone marrow and the blood. "Representative PCR gel results revealed three specific bands corresponding to HoxB5, HoxA9, and Meis1, indicating that these driving oncogenes were gnomically integrated into the leukemia cells and suggesting their involvement in leukemia generated in ML23 mice." (PMID 33602907, 2021). "The HoxB5, HoxA9, and Meis1 oncogenes were inserted into ML-23 leukemic cell line DNA, which suggests that they were involved in inducing AML-like leukemia in our model." (PMID 33602907, 2021). "Interestingly, the group with increased HOXB5 gene expression had a higher leukemia stem cell (LSC) score reported by a previous study, which indicated that HOXB5 might be important for LSC functions." (PMID 34421991, 2021).
lymph node metastasis (2 papers, 2021). "HOXB5 expression was associated with high T stage, lymph node metastasis, and high Gleason score and in TCGA (PRAD) database." (PMID 34440097, 2021). "In both cohorts, elevated expression of HOXB5 positively correlated with lymph node metastasis, distant metastasis, poor tumor differentiation and advanced AJCC stage." (PMID 33456563, 2021). "In both cohorts, HOXB5 expression positively correlated with CXCR4 and ITGB3 expression, and elevated expression of CXCR4 and ITGB3 positively associated with lymph node metastasis, distant metastasis and advanced AJCC stage." (PMID 33456563, 2021).
multiple myeloma (2 papers, 2021 to 2023). "Moreover, we detected aberrant overexpression of HOXB5 in subsets of Burkitt lymphoma, FL, and multiple myeloma patients, confirming the clinical relevance of its deregulation." (PMID 37371852, 2023). "We then used the Cancer Cell Line Encyclopedia and Genomics of Drug Sensitivity in Cancer databases to analyze the correlation between HOXB5 gene expression and bortezomib, the clinically approved agent for multiple myeloma with activity to inhibit the NF-κB pathway." (PMID 34421991, 2021).
prostate carcinoma (2 papers, 2021). A carcinoma that arises from epithelial cells of the prostate gland. "A ceRNA network analysis of prostate cancer established a network consisting of four hub genes, homeobox B5 (HOXB5), glypican 2 (GPC2), pepsinogen A-5 (PGA5), and ameloblastin (AMBN), which are strongly associated with patient survival." (PMID 34681112, 2021). "However, the biological role of HOXB5 in prostate cancer (PCa) is not fully elucidated." (PMID 34440097, 2021).
Alzheimer disease (1 paper, 2013). A progressive, neurodegenerative disease characterized by loss of function and death of nerve cells in several areas of the brain leading to loss of cognitive function such as memory and language. "Hoxb5 was found up-regulated in incipient Alzheimer's disease." (PMID 23433062, 2013).
Arboleda-Tham Syndrome (1 paper, 2022). "The second overlaps part of HOXB5 and HOXB6 and is also hypomethylated in Arboleda-Tham Syndrome patients." (PMID 36064314, 2022).
asthma (1 paper, 2021). "Further, in a study using Hox5 compound null alleles (Hoxa5+ ⁣/−; Hoxb5–/–; Hoxc5+ ⁣/−), mice present with an increased Th2 cells response and exacerbated lung tissue pathology in asthma models." (PMID 34901011, 2021).
atherosclerosis (1 paper, 2024). A disease characterized by the build-up of fatty material and calcium deposition in the arterial wall resulting in partial or complete occlusion of the arterial lumen. "Further studies are needed to determine the molecular relationship between Hoxb5/6 and the adjacent lncRNA ENSMUST00000140952 in MASMC and atherosclerosis." (PMID 38660676, 2024).
B-cell lymphoma (1 paper, 2023). "While aberrant activation of miR10a reduced BCL6 in B-cell lymphoma, the role of HOXB5 remained unclear." (PMID 37371852, 2023). "Comparative gene expression profiling analysis of SC-1 versus seven B-cell lymphoma control cell lines demonstrated elevated HOXB5 activity and revealed high expression levels of ZNF521 in SC-1." (PMID 37371852, 2023). "We have shown that ZNF521 activates HOXB5 expression, supporting a potential stem cell role oncogenically reactivated by HOXB5 in B-cell lymphoma." (PMID 37371852, 2023). "Here, we identified HOXB5 representing another member of the HOXB gene cluster aberrantly expressed in B-cell lymphoma." (PMID 37371852, 2023). "Collectively, we characterize triple-hit B-cell line SC-1 and identify the aberrant expression of HOXB5 and miR10a, both novel oncogenes in B-cell lymphoma." (PMID 37371852, 2023). "To study HOXB5 expression in B-cell lymphoma patients, we exploited public gene expression profiling datasets." (PMID 37371852, 2023). "Therefore, impacting the function of BCL6 via HOXB5 or miR10a as shown here, may well be of tumorigenic relevance, both in SC-1 cells and more generally in B-cell lymphoma." (PMID 37371852, 2023).
ciliopathy (1 paper, 2019). A genetic disorder of the cellular cilia or the cilia anchoring structures, the basal bodies, or of ciliary function. "The observations of increased Hoxb5 gene expression in the Tmem67−/− cerebellum and increased occupancy of Hoxb5 at the β-catenin promoter therefore provide a mechanistic explanation for increased canonical Wnt/β-catenin signalling in the ciliopathy disease state." (PMID 30931988, 2019).
colorectal adenocarcinoma (1 paper, 2024). The most common type of colorectal carcinoma. "Moreover, comparing the samples from young and old donors, four DEGs (HOXB5, KRT8, MSX1, NFE2L3) in the samples from old donors were specifically expressed in colorectal adenocarcinoma (4/33, 12%)." (PMID 38520027, 2024).
Insulin resistance (1 paper, 2025). Increased resistance towards insulin, that is, diminished effectiveness of insulin in reducing blood glucose levels. "In summary, we have identified disrupted circadian rhythms in key genes (PER3, ARNTL, TSSK6, HOXB5) in skeletal muscle cells from individuals with T2D, advancing current understanding of how intrinsic timekeeping mechanisms contribute to insulin resistance." (PMID 40495716, 2025).
papillary thyroid carcinoma (1 paper, 2021). "A recent study showed that HOXB5 was regulated by miR-221 in papillary thyroid carcinoma." (PMID 34440097, 2021).
renal carcinoma (1 paper, 2021). A carcinoma arising from the epithelium of the renal parenchyma or the renal pelvis.
thyroid carcinoma (1 paper, 2013). "Hoxb5 has been identified as a target of miR-221 in thyroid carcinoma, and Hoxa5 as a target of miR-130a in human umbilical vein endothelial cells (HUVEC) cells." (PMID 23409087, 2013). "Hoxb5 is a target of miR-221 in human thyroid carcinoma cells." (PMID 23409087, 2013).
tongue squamous cell carcinoma (1 paper, 2022). A squamous cell carcinoma that arises from the tongue. "In tongue squamous cell carcinoma (TSCC), the PRNCR1/miR-944/HOXB5 axis promotes the tumor cell proliferation, invasion, and migration, and inhibits apoptosis, while the PRNCR1/miR-944/HOXB5 axis can also promote tumor growth in the SCC-9 xenograft nude mice." (PMID 36077769, 2022).
cancer (24 papers, 2007 to 2025). A tumor composed of atypical neoplastic, often pleomorphic cells that invade other tissues. "We found that the expression of the HOXB5 mRNA with the 1010G allele was significantly higher than the mRNA with the 1010A allele in both cancer tissues and cell lines (Figure 4A1 and A2)." (PMID 22768238, 2012). "As cancer cell proliferation at primary and metastatic sites are two critical steps in the metastatic cascade, HOXB5-enhanced cell proliferation may be an underlying mechanism for HOXB5-mediated CRC metastasis." (PMID 33456563, 2021). "High expression of genes such as HOXB5, HOXC11, HOXA13, HOXD13, HOXA6, and HOXC6 in certain cancers is linked to poor overall survival (OS)." (PMID 39980564, 2025). "Previous studies revealed that EGFR is one of the genes mainly regulated by HOXB5 in cancer progression." (PMID 35847904, 2022). "HOXB5 regulated cancer cell proliferation via different signaling pathways, mainly including Wnt/β-catenin and Akt pathways." (PMID 35847904, 2022). "HOXB5 is also a master target of multiple cancer-related microRNAs (miRNAs), further proving the central role of HOXB5 in cancer development." (PMID 35847904, 2022). "In retinoblastoma (RBM), HOXB5 significantly contributes to the migration and invasion of cancer cells by stimulating the activation of the ERK1/2 pathway and subsequent production of the proteases MMP-3 and MMP-13." (PMID 34617205, 2022). "Some recent studies revealed that this downregulated miRNA was detected to have an essential effect on cancer cell proliferation, migration, invasion, metastasis, and angiogenesis through targeting multiple oncogenic genes HOXB5, WNT7B and LncRNA HAND2-AS1." (PMID 33910530, 2021). "HOXB5 is a transcription factor that is overexpressed in several cancers and participates in the proliferation, migration, and invasion of cancer cells." (PMID 33858489, 2021). "Meanwhile, HOXB5 functions as an oncogene in several cancers like breast cancer 21, retinoblastoma 22, and small cell lung cancer." (PMID 33897880, 2021). "It is noteworthy that HOXB5 can promote metastasis through different molecular mechanisms in other cancer types." (PMID 33897880, 2021). "In fact, our rescue experiments proved that miR-507 downregulation or HOXB5 upregulation eliminated the cancer-inhibiting effects of si-PRRT3-AS1." (PMID 37304647, 2021). "HOXB5, as a member of the homeobox gene family, is a vital transcription factor, and HOXB5 overexpression is significantly correlated with cancer progression and a poor prognosis." (PMID 33858489, 2021). "Recent studies confirmed that HOXB5, a member of the homeobox gene family, is overexpressed and promotes cell proliferation and migration in various cancers, including breast, lung, and gastric carcinoma." (PMID 33858489, 2021). "P4HA2 is a precursor of collagen and a metastasis marker and HOXB5 is a homeobox transcription factor whose overexpression has been found in several malignant tumors." (PMID 24548329, 2014). "To further explore the potential role of HOXB5 in tumorigenesis, we investigated the effect of HOXB5 on colony formation of cancer cells in vitro." (PMID 22768238, 2012). "The HOXB5 gene, which was found to be involved in lung and gut development, was reported to be an important factor in human disease, including cancers." (PMID 22768238, 2012). "Given that dysregulation of miRNAs is a key characteristic of HCC, and HOXB5 is also a master target of multiple cancer-related miRNAs, we determined whether upregulation of HOXB5 in HCC is a result of dysregulation of certain miRNAs." (PMID 35847904, 2022). "Abnormal expression of HOXB5 human cancers, including that in HCC, had been reported previously." (PMID 35847904, 2022). "Considering that HOXB5 is a master target of multiple cancer-related miRNAs, we raised the question of whether certain miRNAs regulate HOXB5 expression in HCC progression." (PMID 35847904, 2022).